APC (APC regulator of Wnt signaling pathway)
Diseases named in the same sentence as APC in open-access papers (continued):
Sharing a sentence is not in itself a finding about the gene and the disease.
tumor (continued). "In approximately 1% of the cases we identify insertions in APC, likely to be tumor-initiating events." (PMID 31492840, 2019). "Most germline mutations are also truncating (e.g., frameshift, nonsense), confirming APC’s tumor suppressor role." (PMID 31382613, 2019). "The famous tumor suppressor APC which co-appears with ‘cancer’ for 2016 times, with ‘prostate’ for 59 times ranks in the 29th in our method, while 183th in IntDriver, 71th in DriverNet and is missed by DawnRank, Muf_max and Muf_sum." (PMID 31088372, 2019). "The primary tumor suppressive role of APC is to negatively regulate the WNT signaling pathway via its role as a scaffold for the β-catenin destruction complex." (PMID 31623618, 2019). "MYC mRNA levels were higher in 39 of the 41 tumor samples than the normal mucosa of the same patients, while APC mRNA levels were lower in the majority of cancer samples." (PMID 31623618, 2019). "Adenomatous Polyposis Coli (APC) is a 312 kDa protein that functions as a tumor suppressor by acting as a requisite scaffolding protein that stabilizes the β-catenin destruction complex." (PMID 31231471, 2019). "The APC gene codes for the APC protein that acts as a tumor suppressor, which means that it keeps cells from growing and dividing too fast or in an uncontrolled way." (PMID 30123409, 2018). "Presence of pre-operative DAPK methylation was associated with poorer survival (p = 0.01) and detection of post-operative methylation of APC promoter was correlated with residual tumor (p = 0.03)." (PMID 30087854, 2018). "The median overall survival rate for patients with a tumour harbouring APC/CTNNB1/ZNRF3 alteration was significantly lower compared to the ones without (43 vs 114 months, log rank p = 0.0141)." (PMID 29872083, 2018). "Here we exploit vulnerabilities in APC mutant stem cells and use chemo-preventative strategies to influence tumour initiation in the mouse intestinal epithelium." (PMID 30405205, 2018). "We have previously discovered and/or characterized tumor-specific DNA methylation of six genes (APC, GSTP1, HOXD3, KLK10, TBX15, and TGFβ2) in radical prostatectomy tumor samples." (PMID 30470249, 2018). "The APC gene is a tumor suppressor gene that produces APC protein, a multifunction protein which controls how quickly cells grow and prevent the development of tumors." (PMID 29743854, 2018). "The APC protein performs multiple tumor suppressor functions including negative regulation of the canonical WNT signaling pathway by both cytoplasmic and nuclear mechanisms." (PMID 30131849, 2018). "In conclusion, APC+/min tumor-bearing mice show a higher accumulation of integriSense750 probe in comparison to WT mice, suggesting that more fluorescent signal corresponds to an increased tumor load in APC+/min mice." (PMID 30140377, 2018). "Amongst 16 CTNNB1 wildtype tumours with the presence of nuclear accumulation, five harboured ZNRF3 deletion and one harboured APC mutation." (PMID 29872083, 2018). "The strong reduction of APC levels initiated tumour formation along the intestine, including the colon." (PMID 30209039, 2018). "The deleted region, that contains domains for the association with β-Catenin and microtubules, has been considered essential for the tumor suppressor activity of APC." (PMID 29549256, 2018). "Axin and APC are the tumor suppressor genes that bind β-catenin and recruit CK1 to facilitate destruction of β-catenin through phosphorylation." (PMID 29433490, 2018).
tumor (continued). "Among the alterations in the APC expression, the epigenetic modifications cause a downregulation in its expression in OSCC leading to a blockage of tumor suppressor action and a progress of tumorigenesis." (PMID 29976158, 2018). "Both APC and KRAS mutations synergistically promote cellular transformation and tumor growth, which is attributed to the activation of the RAS-ERK pathway via the aberrant activation of the Wnt/β-catenin signaling caused the loss of APC6–8." (PMID 30459318, 2018). "For example, the first rate limiting enzyme, ODC, is negatively regulated by the adenomatous polyposis coli (APC) tumor-suppressor gene in colonic mucosal tissue." (PMID 29518931, 2018). "In our study, the association was even more evident in the group of patients with tumour harbouring alterations in APC/CTNNB1/ZNRF3." (PMID 29872083, 2018). "Of note, at this latter time point (4 weeks), IntegriSense750 accumulation is significantly higher in DSS-treated APC+/min tumor-bearing mice compared to DSS-treated WT mice." (PMID 30140377, 2018). "Using a next generation sequencer (NGS), loss of heterozygosity (LOH) of the adenomatous polyposis coli (APC) gene was detected in the tumor." (PMID 29535845, 2018). "UC-associated neoplasia frequently showsTP53 or KRAS mutations, while mutations of the APC gene are rarely observed." (PMID 29652830, 2018). "The tumor suppressors APC and Axin form the core of the multiprotein destruction complex, which targets the Wnt-effector beta-catenin for phosphorylation, ubiquitination and destruction." (PMID 29641560, 2018). "We also confirmed the mutation of the APC gene by Sanger sequencing and the expression of APC protein by immunohistochemical staining in tumor tissue samples from the patient." (PMID 29535845, 2018). "LOH of the adenomatous polyposis coli (APC) gene has been reported in several neoplasia, including SCC." (PMID 29301290, 2018). "Adenomatous polyposis coli (APC) is an important tumor suppressor gene with an inhibitory function on Wnt/ß-catenin signaling." (PMID 30469518, 2018). "Median age at operation and tumour size for the group of tumours with APC/CTNNB1/ZNRF3 alterations were 52.5 years and 10 cm respectively and were not significantly different from those without mutations (46 yrs, p = 0.3517, and 10 cm, p = 0.5731)." (PMID 29872083, 2018). "Tumor suppressors like Axin, APC etc. has been reported to govern proteasomal degradation of β-catenin and thus attenuates Wnt/β-catenin activities." (PMID 29765542, 2018). "Loss of heterozygosity at the APC tumor suppressor locus is an early event in CRC development, whereas germline APC mutation leads to the familial adenomatous polyposis syndrome." (PMID 30028958, 2018).
tumor (continued). "Mutations of CTNNB1, APC and FBXW7 were detected in 9 (10.5%), 20 (23.2%), and 17 (19.8%) tumor samples, respectively." (PMID 29402328, 2018). "For instance, genes such as KRAS, PTEN and APC are well-known tumor drivers in several types of cancer." (PMID 29621323, 2018). "The tumor suppressor activity of APC has been extensively studied in the setting of epithelial transformation." (PMID 29946544, 2018). "APC is a tumor suppressor which promotes rapid degradation of CTNNB1 and participates in Wnt signaling as a negative regulator." (PMID 28415609, 2017). "Our data echo a recent study showing that minimal APC restoration is sufficient for tumor suppression." (PMID 29045831, 2017). "APC is a crucial factor negatively regulating Wnt signalling in the process of tumor formation and cell development, which forms the destruction complex through the combination with the kinases CK1 and GSK3 and the scaffold Axin to target β-catenin." (PMID 28275205, 2017). "We observed substantially improved survival with high lifetime prediagnostic RPA in women with a tumor-methylated APC, CCND2, HIN1, or TWIST1 gene promoter compared with active women with unmethylated gene promoters." (PMID 28222775, 2017). "Significant differences were also found between the methylation status of APC in tumors and that in tumor-adjacent tissues (p = 0.001), tumor-distant tissues (p = 0.001) and breast tissues from healthy women (p = 0.003)." (PMID 28403857, 2017). "Three non-REF source elements (on Chromosomes 17, 14, and 12) produced the majority of somatic L1 insertions in this tumor, including an insertion that disrupted the APC TSG and initiated tumorigenesis." (PMID 28561751, 2017). "The human APC (adenomatous polyposis coli) gene is a tumor suppressor gene located on the long (q) arm of chromosome 5 and it encodes a protein of 312 kDa with 2843 amino acids." (PMID 28576136, 2017). "Gain-of-function mutations in the CTNNB1 gene, as well as loss-of-function mutations in the APC and AXIN2 genes, activate the canonical Wnt/β -catenin signaling cascade that regulates self-renewal, survival, proliferation and differentiation of tumor cells." (PMID 29312609, 2017). "Our results demonstrated that miR-125b played an important role in triggering tumor invasion through activation of the Wnt/β-catenin signal pathway by targeting APC gene." (PMID 28176874, 2017). "Current evidences suggest that MSI1 regulates stem cell functions in both normal and malignant colorectal cells, by transcriptionally suppressing genes with the tumor suppressor functions, such as Lrig1, Bmpr1a, Cdkn1a, Pten, p21, Numb and APC." (PMID 29064439, 2017). "For instance, APC is a tumor suppressor protein that regulates β-catenin, a major component of the Wnt signaling pathway, and suppresses tumor progression." (PMID 28702009, 2017). "Disrupting the balance between β-catenin and APC frequently also results in cancer progression by driving cell transformation, tumor angiogenesis, and metastasis." (PMID 28245560, 2017). "Taken together with our CRISPR-engineered cell line data, the results support the notion that CID is the critical threshold in APC for the pathological level of Wnt activation and tumor transformation." (PMID 29045831, 2017).
tumor (continued). "APC functions as an important tumor suppressor gene that antagonizes Wnt/β-catenin signaling pathway." (PMID 28176874, 2017). "Reassuringly, the resulting list includes several known colon tumor suppressors such as APC, TCF7L2, MCC, PTEN, and SMAD4." (PMID 29196508, 2017). "We show that USP7-mediated β-catenin deubiquitination is a tumor-specific event when APC is truncated and that it is RNF220 independent." (PMID 29045831, 2017). "APC is coded for genetically by two alleles, each of which is either healthy or mutated; the majority of CRC tumours display inactivation of both alleles." (PMID 28245235, 2017). "Knockdown of miR-19a in CRC cells with compromised APC function reduces cell growth, migration and invasion and enforced expression of miR-19a overrides APC tumor suppressor activity." (PMID 29137282, 2017). "Most CRC tumours (≈80%) are hemizygous for C‐terminal truncations of APC, focussed at a hotspot area known as the mutation cluster region." (PMID 28910490, 2017). "On the other hand, CDC27 is an inducing factor for TGF-β, which modulates APC/C activity via phosphorylation, thereby resulting in the induction of genes responsive for growth inhibition and tumor suppression." (PMID 27974673, 2017). "USP7 depletion in APC-mutated CRC inhibits Wnt activation by restoring β-catenin ubiquitination, drives differentiation, and suppresses xenograft tumor growth." (PMID 29045831, 2017). "Six tumor-associated genes (RASSF1A, APC, BVES, TIMP3, GSTP1, and HOXA9) were selected as candidates." (PMID 28951629, 2017). "Our studies support a mechanism whereby OATP2A1 expression in the endothelial vasculature of the tumour, is required for maximal tumorigenesis in the APC mutant (Apc∆716/+) mouse model." (PMID 29185482, 2017). "We find that the β-catenin inhibitory domain (CID) in APC represents the threshold for pathological levels of Wnt activation and tumor transformation." (PMID 29045831, 2017). "In APC mutant tumor cells, Pygo serves as a nuclear anchor protein that binds with BCL-1 and drives the nuclear entry of β-catenin." (PMID 29050252, 2017). "Although analyzed separately, these additional samples corroboratedthe mutations above and highlighted additional recurrent mutations in theBRCA2, MLL3, APC,NF1, and ELF3 tumor-suppressor genes." (PMID 28297679, 2017). "The same is true for the APC tumor suppressor (>29x), a BCL9-specific hit that is recruited to TCF target genes upon Wnt signaling by β-catenin, owing to direct high-affinity binding." (PMID 28296634, 2017). "Vitamin D is implicated in the etiology of cancers of the gastrointestinal tract, usually characterized by alteration in the APC/β-catenin/TCF tumor suppressor pathway." (PMID 27768599, 2016). "Transcriptional changes induced by pulsing bone marrow-derived DCs with whole tumour lysate were examined by a pathway-specific APC gene array." (PMID 26795765, 2016). "SIAH1 has emerged as a tumor suppressor, inhibits cell proliferation and promotes apoptosis, by binding with APC and promoting the degradation of β-catenin." (PMID 27494869, 2016). "The APC tumor suppressor is a negative regulator of free CTNNB1, a central player of WNT signaling, and up to 80% of CRCs have mutations in the APC gene resulting in a truncated protein." (PMID 26623728, 2016).
tumor (continued). "Knockdown of FZR1 or inhibition of the APC/C with proTAME has been reported to enhance the sensitivity of a number of tumour cell lines to the topoisomerase II inhibitor etoposide, through an increase in APC/CFzr substrate TopIIα." (PMID 27655696, 2016). "Mutations in APC, AXIN2, or CTNNB1 are believed to change a proliferating tissue into invasive and ever-expanding neoplasm that shows submucosal invasion and causes systemic metastases." (PMID 27713700, 2016). "The tumor suppressor APC is a key negative regulator of Wnt signaling and down regulates the protein levels of β-catenin, the transcriptional co-activator of Wnt target genes." (PMID 27486871, 2016). "Additional, cDNA array and in silico analyses of prostate cancer tissue suggested that rs2707765 affects APC expression, which in turn is correlated with tumor aggressiveness and patient prognosis." (PMID 27898031, 2016). "In recent years, the study of cancer suppressor gene APC is paid more and more attention to in-depth study of tumor." (PMID 27065015, 2016). "Allograft tumours derived from APC/KRAS/PTEN spheres were also sensitive to sequential treatment: strikingly, three of five allograft tumours showed regression in response to 0.01 mg kg−1 bortezomib followed by BEZ235." (PMID 27897178, 2016). "This is consistent with the so-called gatekeeper function of the APC tumour suppressor, which inhibits the initiation of (or entry into) carcinogenesis." (PMID 27562646, 2016). "We quantified methylation of the APC promoter region in tumor and matched normal colonic mucosa of 47 randomly selected patients from both Ontario and Newfoundland." (PMID 26884349, 2016). "Recently study demonstrated loss of PTEN, a well-known tumor suppressor, reduces stabilization of PFKFB3 by enhancing APC/C–Cdh1-mediated degradation." (PMID 27418942, 2016). "The adenomatous polyposis coli (APC) gene located at chromosomal band 5q21–q22 is a classical tumor suppressor gene." (PMID 27191268, 2016). "For example, hypermethylation of the adenomatous polyposis coli (APC gene promoter (a tumor suppressor gene) in human term placenta suggests that silencing of tumor suppressor genes is an integral part of normal placental development." (PMID 27500275, 2016). "Rare somatic variants with frameshift mutations on APC and cetuximab resistance mutation on KRAS were identified in the tumor tissues." (PMID 27121310, 2016). "The adenomatous polyposis coli (APC) tumor suppressor is a multifunctional regulator of Wnt signaling and acts as a mobile scaffold at different cellular sites." (PMID 27144584, 2016). "APC promoter methylation is rarely observed in normal colonic tissue compared with CRC tumor tissue in our study population, which replicates the findings of a recent meta-analysis." (PMID 26884349, 2016). "This complex is composed of two negative regulatory kinases, including Glycogen Synthase Kinase 3β (GSK-3β) and at least two anchor proteins that also function as tumor suppressor proteins, namely Axin1 or Axin2 and APC (adenomatous polyposis coli)." (PMID 27571104, 2016). "Nowadays, the APC protein is considered a universal tumour suppressor mostly acting as an antagonist of the Wnt signaling pathway." (PMID 28105931, 2016). "As we show, JNK activation in APC−/− cells and in patches of surrounding tissue is important to drive tumor growth." (PMID 26853366, 2016).